MMP9 (matrix metallopeptidase 9)
Diseases named in the same sentence as MMP9 in open-access papers (continued):
Sharing a sentence is not in itself a finding about the gene and the disease.
lymph node metastasis (continued). "We examined the effects of MMP-9 gene knockdown not only in terms of nearby lymph node metastasis but also in terms of distant lymph node inguinal lymph node metastasis." (PMID 33828938, 2021). "MMP2 overexpression conferred a higher risk to distant metastasis (OR = 2.69, 95% CI 1.35–5.39, P = 0.005) and MMP9 overexpression correlated with lymph node metastasis (OR = 2.90, 95% CI 1.86 – 4.53, P < 0.001)." (PMID 33568081, 2021). "Among MMPs, MMP-2 and MMP-9 are collagenase that can selectively degrade type IV collagen, a major component of ECM; overexpression of MMP-2 or MMP-9 is associated with more lymph node metastases, distant metastases and poor survival in head and neck SCC." (PMID 31850235, 2019). "FLNA has also been shown to be significantly correlated with lymph node metastasis, disease stage, histological grade, and poor OS through promotion of the degradation of MMP-9." (PMID 30872976, 2019). "The univariate Cox regression analysis also showed that age, pathological classification, depth of invasion, lymph node metastasis, distant metastasis, TNM stage, and TIMP-2 or MMP-9 expression were associated with OS of CRC patients." (PMID 31293204, 2019). "Our results showed that cases with overexpression of both VEGF-C/MMP-9 had a significantly greater depth of invasion, lymphatic and lymph node metastasis, worse histological grade and TNM stage." (PMID 31824776, 2019). "Kaplan-Meier analysis showed that MMP-9, Bismuth-Corlette classification, Lymph node metastasis, Portal vein invasion, Hepatic artery invasion, Liver invasion, Incised margin, and Preoperative biliary drainage were related to prognosis." (PMID 31038586, 2019). "We also noted a connection between MMP-9 and lymph node metastasis, depth of invasion, and TNM stage." (PMID 31824776, 2019). "High levels of MMP-2 and MMP-9 in serum were strongly connected with lymph node metastasis and, additionally, activities of MMP-2 and MMP-9 were significantly increased in metastatic than in non-metastatic lymph nodes." (PMID 27110764, 2016). "It has been demonstrated that MMP-2 and MMP-9 expression is positively correlated with the depth of invasion, lymph node metastasis, and vessel permeation." (PMID 25617627, 2015). "They demonstrated that high levels of MMP-9 protein were positively correlated with the status of lymph node metastasis (N classification) (P = 0.002) and clinical stage (P < 0.001) of NPC patients." (PMID 29147412, 2015). "This overexpression was associated with lymph node metastasis (P = 0.008), tumor differentiation (P = 0.020), distant metastasis (P = 0.026), MMP-2 (P = 0.035), and MMP-9 expression (P = 0.022)." (PMID 26599012, 2015). "The co-expression of MMP-9 and TN-C was correlated with lymph node metastasis (P < 0.001, χ2 = 13.15), vascular invasion (P = 0.003, χ2 = 8.53), hepatic metastasis (P < 0.001, χ2 = 15.64) and TNM stage (P < 0.001, χ2 = 25.06)." (PMID 26652622, 2015). "A number of previous studies have found that the high expression of VEGF and MMP-9 closely correlate with lymph node metastasis." (PMID 24396477, 2014). "Cox regression models were used to analyze the effect of clinicopathological parameters on patient survival time, and the parameters included age, gender, levels of VEGF and MMP-9, histological type, grading, lymph node metastasis and tumor location." (PMID 24396477, 2014). "The levels of VEGF and MMP-9 were shown to correlate with the clinical stage, tumor size and the lymph node metastasis status." (PMID 24944618, 2014). "Previously, several studies have shown augmented MMP-9 expression in differentiated thyroid carcinoma, demonstrating a correlation between MMP-9 levels and lymph node metastasis." (PMID 24527080, 2014). "MMP-9 was found to be upregulated in response to BQCS and MMP-9 expression was also associated with neck lymph node metastasis, thus implying a significant role of MMP-9 in the progression of OSCC among patients with a history of BQ use in Taiwan." (PMID 22912735, 2012).
lymph node metastasis (continued). "Expression of MMP-9 has been found to correlate with tumor invasiveness and metastasis, including lymph node metastasis." (PMID 19804631, 2009). "VEGF expression was down-regulated in Late Stage lymph node metastasis, while MMP-9 expression was elevated in Early Stage metastasis." (PMID 10424737, 1999). "Moreover, the upregulation of MMP-2 and MMP-9 has been consistently reported in OSCC patients with lymph node metastasis." (PMID 39408625, 2024). "Furthermore, CCR7 expression exhibited the highest prediction accuracy (AUC 95.7%) and sensitivity (100%) in predicting the lymph node metastasis in LSCC compared to that of MMP-9 (AUC 92.9%, sensitivity 90%)." (PMID 37600570, 2023). "Therefore, this investigation is done to know the role of MMP9 in predicting lymph node metastasis in oral squamous cell carcinoma (OSCC)." (PMID 36756017, 2023). "We observed significant publication bias in the analysis of the association of MMP2 overexpression with survival (P < 0.05), ER status (P = 0.003), and lymph node metastasis (P = 0.003), as well as MMP9 overexpression with lymph node status (P = 0.045) and TNM stage (P = 0.042)." (PMID 33568081, 2021). "MMP-9 is highly expressed in a variety of tumor tissues, including gastric cancer, breast cancer, prostate cancer, osteosarcoma, and non-small-cell lung cancer, and is correlated with clinical classification, lymph node metastasis, and overall survival rates." (PMID 33828938, 2021). "We found that MMP-9 expression was only associated with lymph node metastasis, but not with other clinical characteristics." (PMID 24845596, 2014). "In addition, the levels of VEGF and MMP-9 were found to closely correlate with lymph node metastasis (VEGF, P<0.0001; MMP-9, P<0.0001) in the pretreatment group, while being independent of other clinicopathological parameters (P>0.05)." (PMID 24396477, 2014). "Elevated MMP-9 expression was correlated with lymph node metastasis and LMVD (P<0.05)." (PMID 24845596, 2014). "On the other hand, immunoexpression of active MMP-9 was positively correlated with lymph node metastases, extrathyroid invasion, and degree of neoplastic infiltration, as indicated both by χ2 test (or Fisher exact test when necessary) and Spearman’s correlation analysis." (PMID 24778099, 2014). "In our study, MMP-9 expression was significantly associated with LMVD and lymph node metastasis." (PMID 24845596, 2014). "There is an obvious correlation between IL-8 expression and lymph node metastasis, IL-8 may facilitate the lymph node metastasis by up-regulating MMP-9 expression." (PMID 20704821, 2010). "However, we observed that the expression level of MMP9 was positively correlated with the status of lymph node metastasis (N classification) (N0-N1 vs. N2-N3) (P = 0.002), and clinical stage (I-II vs. III-IV) (P < 0.000) in NPC patients." (PMID 20534121, 2010). "In addition, high levels of MMP9 protein were positively correlated with the status of lymph node metastasis (N classification) (P = 0.002) and clinical stage (P < 0.001) of NPC patients." (PMID 20534121, 2010). "Moreover, we demonstrated that NGAL mRNA up-regulation correlated significantly with MMP-9 and some important clinicopathological characteristics such as depth of invasion, lymph node metastasis, venous involvement and advanced pTNM stage (p < 0.05)." (PMID 19419554, 2009). "Furthermore, expression of some MMPs such as MMP-9 appears to vary not only between the primary tumor and sites of lymph node metastasis, but also between the early and late stages of lymph node metastasis." (PMID 15291964, 2004). "Slug and Vimentin levels were significantly increased in patients with T-stage ≥ T3, while patients who had lymph node metastasis had significantly higher HAS-2, SNAI1, TWIST1, N-Cadh, Slug, and MMP-9." (PMID 40149256, 2025).
lymph node metastasis (continued). "Another CTSK expression upregulation is GC in which coronin 3 promotes metastasis through upregulation of MMP-9 and CTSK expression and shows a strong link with GC lymph node metastasis and unfavorable prognosis." (PMID 37930479, 2023). "MMP-9 is a highly expressed gene in COAD, and its expression level is positively correlated with the pathological stage, lymph node metastasis and prognosis of patients." (PMID 37543674, 2023). "The analysis of MMP-9 and CCR7 expression performed in this study has extended our knowledge on the potential of these markers in predicting the lymph node metastasis in LSCC." (PMID 37600570, 2023). "The expression of both MMP-9 and CCR7 was significantly correlated with the lymph node metastasis in LSCC (P<0.001)." (PMID 37600570, 2023). "The current study revealed FN1, MMP9, and CXCL8 as potential biomarkers for identifying and predicting lymph node metastases." (PMID 37640804, 2023). "IL-17, MMP-9 and CD23 was related to TNM staging, differentiation degree, lymph node metastasis, and infiltration degree (P<0.001)." (PMID 32461933, 2020). "Recently, it was reported that ZNF185 expression is negatively correlated with lymph node metastasis of lung adenocarcinoma and its overexpression leads to down-regulation of p-AKT, p-GSK3β, VEGF and MMP-9 expression." (PMID 30446632, 2018). "Horikawa and colleague found that the expression of MMP-9 had a significant positive correlation with the expression of LMP1 (P = 0.0001) and the expression of MMP-9 significantly correlated with lymph node metastasis (P = 0.0004)." (PMID 29147412, 2015). "Within this group of proteases, only MMP9, MMP13, MMP14, and TIMP1 have correlated with depth of tumoral invasion, lymph node metastasis, and an unfavorable prognosis in GC patients." (PMID 24669030, 2014). "The incidence of lymph node metastasis in patients with high levels of VEGF or MMP-9 has been reported to be higher compared with patients with low levels of VEGF and MMP-9." (PMID 24944618, 2014). "When comparing the MMP-9 status with clinicopathological variables, we found significant positive correlations between MMP-9 expression and lymph node metastasis (P = 0.020), and Dukes’ stage (P = 0.029)." (PMID 24476461, 2014). "Some studies have suggested a correlation of MMP9 expression with poor prognosis or lymph node metastasis, while others have reported no clear correlation with the prognosis or clinicopathological factors of PDACs." (PMID 39158384, 2024). "The degradation of extracellular matrix caused by MMPs is critical and the results suggest that ALIX could contribute to increased MMP-9 and MMP-14, leading to lymph node metastasis." (PMID 38203696, 2023). "Several studies in the literature have shown the increased expression of MMP-9 in CRC when compared to clinical-pathological variables like stage III and IV, lymph node metastases, distant metastases, peritumoral inflammatory infiltrate and grades of cell differentiation II and III." (PMID 32813775, 2020). "In the present study, the levels of VEGF and MMP-9 were shown to be significantly higher in patients with lymph node metastasis than in patients without lymph node metastasis." (PMID 24944618, 2014). "In conclusion, our results demonstrated that miR-34a expression was significantly correlated with lymph node metastasis and prognosis of TSCC patients and could inhibit migration and invasion of TSCC cell lines via targeting MMP9 and MMP14." (PMID 25268950, 2014). "miR-34a plays an important role in lymph node metastases of TSCC through targeting MMP9 and MMP14 and may have potential applications in prognosis prediction and gene therapy for lymph node metastases of TSCC patients." (PMID 25268950, 2014). "In the present study, the serum levels of VEGF and MMP-9 in the pretreatment group of NSCLC with lymph node metastasis were significantly higher than in those without lymph node metastasis." (PMID 24396477, 2014).
lymph node metastasis (continued). "In oral SCC, the degree of activation of MMP-2 and MMP-9 is significantly higher in malignant tissues of patients with lymph node metastasis than in those without lymph node metastasis." (PMID 24988190, 2014). "The serum and tissue expression of IL-8 and MMP-9 in NSCLC patients with lymph node metastasis was remarkably higher than that without lymph node metastasis." (PMID 20704821, 2010). "MMP-9 and CCR7 might be beneficial as predictors of lymph node metastasis in LSCC patients." (PMID 37600570, 2023). "In addition, the protein levels of VEGF and MMP-9 in patients with lymph node metastasis were significantly higher than those without lymph node metastasis (P<0.001)." (PMID 24944618, 2014).
oral cancer (104 papers, 2008 to 2026). "Several studies have associated an overexpression of MMP-9 with the progression of oral cancer and a poor prognosis." (PMID 38203696, 2023). "Matrix metalloproteinases (MMPs), particularly MMP-9, are linked to this degradation in oral cancers." (PMID 37640804, 2023). "Early metastases are frequently developed in oral cancer, and increased MMP-9 expression is linked to a poorer prognosis." (PMID 37640804, 2023). "The release of MMP-2 and MMP-9 is increased in various types of cancers including oral cancer and their increased levels are associated with poor prognosis." (PMID 32922544, 2020). "Earlier studies have shown that overexpression of MMP9 is observed in oral cancer and is associated with a poor disease-free survival (DFS)." (PMID 32961854, 2020). "MMPs such as MMP-9 or their inhibitors like TIMP-1 are associated with oral cancer metastasis and invasion." (PMID 31772143, 2019). "Taken together, these findings indicate that KLF4 expression promotes oral cancer cell migration and invasion, which is associated with MMP-9 expression." (PMID 26517087, 2015). "In oral cancers, matrix metalloproteinases (MMPs), especially MMP-9, are associated with this degradation." (PMID 23365550, 2013). "The development of early metastases is typical for oral cancer, and increased MMP-9 expression is associated with a poor disease prognosis." (PMID 23365550, 2013). "In oral oncogenesis, it was reported that the MMP-9 polymorphism (-1562 C/T) presents a strong association with increased risk for developing oral cancer in a subset of the general population." (PMID 24455039, 2012). "Increased RRM1 and RRM2 activity was identified in highly metastatic tumour cells, whereas overexpression of RRM2 in human oral carcinoma cells was shown to be associated with increased invasive potential, probably through NF-κB and MMP-9." (PMID 18414411, 2008). "MMP-9 has been implicated as a positive regulator for oral cancer metastasis." (PMID 40017656, 2025). "Our data confirmed that salivary MMP-9 was associated with oral cancer including OSCC." (PMID 33735248, 2021). "Additionally, in oral cancer the role of MMP-9 was purely associated with the degradation of the ECM, which led to the enhancement of carcinoma cell invasion." (PMID 23365550, 2013). "Investigating whether this MMP-9 polymorphism could influence the risk of areca associated oral cancers, it was seen that this DNA modification was linked with OSCC risk only in younger areca chewers." (PMID 24455039, 2012). "In various studies, the expression of MMP-9 has been shown to be an important component of oral cancer tissue, serum and saliva diagnostic markers in the sample." (PMID 39911325, 2025). "TGF-β1 promotes MMP9 mediated oral cancer invasion by upregulating the transcription factor SNAI150." (PMID 39865173, 2025). "Quercetin (50 μM) has also been found to reduce the protein levels of MMP-2 and MMP-9 in oral cancers." (PMID 39335164, 2024). "In line with our findings, previous studies on oral cancer cells have also reported the inhibitory effects of CTX on crucial modulators associated with cell migration and invasion, including MMP-2, MMP-9, and COL1A1." (PMID 39114354, 2024). "These co-cultured oral cancer cells were found to have increased expression, secretion, and activation of pro-matrix metalloproteinase-9 (MMP-9), facilitating increased invasiveness." (PMID 38136355, 2023). "Similar results were observed in the context of oral cancer; Galectin-1 regulated matrix metalloproteinase (MMP)-2 and MMP-9 expression, causing tumor invasion." (PMID 37433225, 2023). "In oral cancer, quercetin increases miR-16 expression levels, which in turn targets MMP-9, MMP-2 and HOXA10, so quercetin can prevent cell proliferation, migration, and survival in oral cancer." (PMID 35971151, 2022). "Among these associations, MMP-2 rs243865 was connected with LC risk and MMP-9 rs3918242 with BC, HCC, LC, and oral cancer risk." (PMID 35574300, 2022).